TLR3 (toll like receptor 3)
Diseases named in the same sentence as TLR3 in open-access papers (continued):
Sharing a sentence is not in itself a finding about the gene and the disease.
infection (continued). "Paradoxically, this TLR3-mediated innate response exacerbates the disease as mice infected with LRV1-bearing Lgy (LgyLRV1+) develop higher lesions and display more parasite burden at the peak of infection when compared to their LRV1-negative counterparts (LgyLRV1-)." (PMID 36034693, 2022). "We demonstrate that productive infection of macrophages can be altered by TLR signaling in response to purified ligands and bacterial coinfection, with TLR2- and TLR5-mediated signaling activating HIV-1 and TLR3- and TLR4-mediated signaling repressing HIV-1 replication in MDMs." (PMID 33472928, 2021). "It is well established that TLR3 plays a positive role in the absence of infection." (PMID 32400961, 2020). "This discrepancy between the Muscovy duck and Shaoxin mallard TLR3 expression data may be due to the strains of virus used in the infection (DK212 vs. DK49; both H5N1) but not age of the birds as both experiments used 4-week old ducks." (PMID 32477965, 2020). "One as-of-yet unsolved aspect of the role of TLR3, TLR7, or TLR9 in detecting retroviruses is that their ligand-binding domains are located within endosomes or on the cell surface, yet release of viral RNA and reverse transcription occurs within the cytoplasm upon infection." (PMID 32751803, 2020). "The expression of the TLR3, TLR5, and TLR6 genes in the liver tissue of infected rhesus macaques was downregulated in the early phase of HEV1 Sar-55 and HEV3-JN83748 infections, while TLR3 gene expression was only upregulated at peak infection and declined during HEV3 infection." (PMID 32731452, 2020). "However, a study using the reconstitution approach showed that HEK293 cells enable to recognize EV-A71 infection to activate type I IFNs only after ectopic expression of TLR3 but not MDA5 or RIG-I." (PMID 31787104, 2019). "To further confirm the importance of the TLR3 signaling pathway in triggering type I IFN antiviral responses to EV-A71 infection, we next investigated the contribution of the TLR3 downstream regulators in linking TLR3 to type I IFN induction during EV-A71 infection." (PMID 30563052, 2018). "Furthermore, results from qPCR analyses showed that the endogenous TLR3 mRNA levels in SK-N-SH cells exhibited no significant reduction at different time points or at different doses of EV-A71 infection." (PMID 30563052, 2018). "Using the Cm model of chlamydial genital tract infection, we infected wild-type and TLR3-/- mice, and compared the vaginal synthesis of cytokines and chemokines, Chlamydia burden, CD4+/CD8+ T-cell profiles, and genital tract pathology at different time points throughout infection." (PMID 29624589, 2018). "All known mammalian TLR except TLR3 use MyD88-dependent pathways, whereas TLR3 exclusively activates TRIF-dependent pathways, and TLR4 is unique in this regard as it can use all four adapter proteins (TRAM, TRIF, TIRAP, MyD88) to signal infection and injury via both pathways." (PMID 28836991, 2017). "However, MSCs treated with the TLR3/dsRNA complex inhibitor did show a reduction in IFN-β and IDO following RSV infection and TLR3 was the only TLR we observed to have significantly increased expression when comparing live infection to UV-inactivated virus." (PMID 27695127, 2016). "Conversely to what has been shown for E75CV1 the progression of the E75-infection resulted in a dramatic imbalance of the immune system by day 7 pi, with the significant up-regulation of 9 genes, namely: IL-5, IL-1β, IL-6, IL-8, IL-10,IL-21, IL-23, DEFB2 and TLR-3." (PMID 26589145, 2015). "Real-time quantitative polymerase chain reaction showed that the expression of TLR3, TLR7, RIG-I, MDA5, IL-1β, IL-2, IL-6, IL-8, IFN-alpha, IFN-beta, IFN-gamma in the lungs was significantly greater than in the respective thymus genes during the early post infection stage." (PMID 26635752, 2015).
infection (continued). "Although it is well known that influenza virus activates both TLR3 and TLR7 pathways, either activation of TLR3 or TRL7 alone could not elucidate the IFN-mediated antiviral defense during infection." (PMID 26206138, 2015). "Infection of peripheral blood mononuclear cells (PBMC) from four breeds of goats and water buffalo resulted in differential viral replication kinetics and inflammatory cytokine profile including IFNα, IFNγ and TNFα with differential activation of TLR3 and TLR7." (PMID 25369126, 2014). "The accumulation of CD11b+Ly-6Chigh leukocytes in the brain was slightly, but not significantly, higher in TLR3−/− mice following IC infection of JEV, as compared to wild-type mice, and TLR4−/− mice showed no significant change in leukocyte accumulation by IC infection of JEV." (PMID 25188232, 2014). "Therefore, an appropriate modulation of respiratory TLR3 could be an interesting therapeutic target not only for reducing RSV-induced lung inflammatory damage, but for avoiding subsequent infections." (PMID 24860569, 2014). "TLR7 and TLR3 were both activated upon LV infection, but not upon Lena infection." (PMID 24643046, 2014). "TLR3-overexpressing HEK293 and HEK293NULL cells could be productively infected with WNV, yielding similar intracellular viral loads and CPE profiles in response to infection." (PMID 25127040, 2014). "Of note, however, CXCL10 production is also induced directly by infection of human AMø by rhinovirus, of murine AMø by RSV and of human MDMø by influenza or HIV, making this cytokine a suitable endpoint to test the functional importance of the observed TLR3 downregulation." (PMID 23497334, 2013). "In contrast, during 24 hours of RSV infection, the levels of TLR3-4 and TLR7-8 were increased from 3 h after RSV infection, and reached to the highest levels at 24 h after infection, whereas TLR9 expression reached a peak level at 12 h after infection with RSV, and then declined." (PMID 24039959, 2013). "RSV infection induces more TLR3 expression and TNFα production than hMPV does, which may partially explain the more severe inflammation observed after RSV infection compared with hMPV infection." (PMID 24039959, 2013). "Chloroquine reduced the effects of RV1B infection but it also reduced RV1B replication suggesting that chloroquine-mediated effects on IFNs may be infection-dependent rather than solely TLR3-dependent." (PMID 23658644, 2013). "On the other hand, no role for TLR3 signaling could be demonstrated during the early immune response of human monocyte-derived dendritic cells after infection with a wild-type isolate of CMV, strain TB40E." (PMID 24023565, 2013). "Thus, apoptosis of infected cells is not required for sensing of infection by adjacent, TLR3 competent hepatocytes." (PMID 23717201, 2013). "Indeed, it was shown that L. (Viannia) panamensis infection results in up-regulation of TLR1, TLR2, TLR3, and TLR4 expression, inducing activation of infected macrophages, whereas infection with L. donovani suppresses the TLR2–NF-κB–mediated pro-inflammatory cytokine response." (PMID 24098824, 2013). "Finally, to confirm that TLR3 expression is critical for antiviral responses to HSV-1 regardless of the route of infection we examined T cell numbers and responses in DLN of TLR3−/− mice following footpad infection." (PMID 24204273, 2013). "Interestingly, two cytosolic PRRs―TLR3 and IFIH1, whose proteins products are involved with the detection of viral PAMPs, such as reoviral double-stranded RNA―were upregulated at the 6 h time point post-infection." (PMID 22455317, 2012). "TLR3 was not significantly induced by virus compared to mock infection." (PMID 23185463, 2012). "However, viral titers were significantly increased in the lungs of Myd88−/− mice (p<0.01), but not Tlr3−/− mice 3 days after infection." (PMID 22496659, 2012).
infection (continued). "We also studied IFN-α production following infection of PBMCs with HSV-1, a virus largely spread among the adult population, as representative of DNA virus and compared IFN-α production with those obtained by triggering two TLRs reported as crucial for immunity to HSV-1, TLR9 and TLR3." (PMID 22768144, 2012). "The authors suggested that during in vivo infection, TLR3 may not encounter reovirus dsRNA or that levels may be too low to efficiently activate TLR3." (PMID 21994762, 2011). "Clinical studies suggest that TLR3 may contribute to the resistance to HCV subtype Ia infection but seems to have no role in disease progression after a chronic infection is established." (PMID 20936107, 2010). "In addition, this suggests that TLR3 signaling on DCs is not sufficient to confer survival following CB4 infection." (PMID 19122812, 2009). "In the absence of infection, TLR3 was found within small vesicles throughout the cytoplasm." (PMID 19247444, 2009). "The amount of neuronal TLR3 was not affected by RABV infection even 48 h after infection." (PMID 19247444, 2009). "On the other end, the absence of a significant TLR3 upregulation and low TLR7 and 9 up-regulation compared to the susceptible mice the infection could hint at a possible mechanism by which LPS could enhance their response to the TMEV." (PMID 19094215, 2008). "Although polymorphisms in the TLR3 gene have not been associated with the presence of symptoms related to HTLV-1 inflammatory diseases, the TLR3 rs3775291 C/T polymorphism seems to contribute to improved control of the infection and inflammatory process among asymptomatic individuals." (PMID 40831704, 2025). "Interestingly, TLR3 may not prevent viral entry into the CNS but instead likely modulates the inflammatory response once the infection is established." (PMID 41267809, 2025). "Thus, it was hypothesized that TLR3 is essential for the proinflammatory response induction and control of DENV infection in different in vitro models, hence possibly indicating that it has a protective role during infection in vivo." (PMID 35632732, 2022). "In support of this hypothesis, the replication rate of passaged viral populations was faster compared to the parental virus in the same infection set-up (MOI 0.05) and in the absence of TLR3-induced response (solid lines and comparing the slope from the time-point 24 h to 48 h post-infection)." (PMID 36271143, 2022). "After IBDV infection, the ECDs of TLR3 could bind to IBDV dsRNA, and the interaction leads to the activation of type I IFN, pro-inflammatory cytokines and chemokines, resulting in the viral elimination or replication in the early infection stage in the BF in the vitro studies." (PMID 35215986, 2022). "Interestingly, we could not see any involvement of TLR2 or TLR3 nor suppression of infection by IFN-β production." (PMID 31867020, 2019). "In addition, our results showed no detectable TLR3 cleavage products after EV-A71 infection or EV-A71 2A expression, suggesting that TLR3 cleavage products may be too unstable to be further degraded in cells." (PMID 30563052, 2018). "In summary, the sequential collaboration of TLR3 and TLR4 to boost the inflammatory cytokine secretion of human monocytes, concomitant with the drastic triggering of cell death, may be a novel strategy for TLR-mediated host innate response to fight pathogen spread after infection." (PMID 29717111, 2018). "In addition, LLT1 induction by TLR agonists (e.g., TLR3, 4, 7, 8, 9) as well as other immune stimuli (such as TCR/BCR cross-linking, mitogens, CD40, etc.)suggests that LLT1 interaction with human NKR-P1A also regulates immune responses during infection, particularly viral and bacterial infections." (PMID 24917862, 2014).
infection (continued). "Collectively, this suggests that while TLR3 may play an important role in viral entry to the CNS and BBB disruption, TLR-independent mechanisms such as RIG-I and MDA5/IPS-1 primarily control the immediate, cellular response to infection, including characteristic, WNV-induced miRNA responses." (PMID 25127040, 2014). "Moreover, infection with the West Nile virus (a retrovirus that produces dsRNA) in mice lacking TLR3 shows reduced microglial activation and more resistance to lethal infection with reduced viral load and inflammatory responses in the brain compared to wild-type mice." (PMID 23935250, 2013). "Thus, the requirement for TLR-3 by RABV may explain why it is upregulated following infection despite the fact that it is not required for a type I IFN response." (PMID 20661430, 2010). "When we inhibited NF-κB and TLR3 separately we did not see an increase in CXCL9 and CXCL10 even following infection with our Hsc70-binding viruses." (PMID 38860860, 2024). "Additionally, upon SFV-GFP infection, LNCaP cells exhibit significantly higher expression of IFN-β and CXCL10 than PANC-1 cells, which could be explained by the elevated levels of RIG-I or TLR3 expression in LNCaP, leading to better RNA-sensing and boosting of subsequent immune responses." (PMID 38425844, 2024). "It should be noted that only the DHX58 gene was upregulated in the head kidney after infection with the wt isolate, whereas no deregulation of RIG-I or MDA5 was observed in any experimental group and TLR3 was slightly upregulated." (PMID 35215144, 2022). "TLR3 also senses HCV infection, and namely, the dsRNA intermediates produced during infection, and not structural HCV RNA." (PMID 36016430, 2022). "Upon the infection of RSV (strain A2) in primary human lung epithelial cells, the knocking down of TLR4, but not TLR3, TLR7, TLR8, or RIG-I results in a reduced expression of pro-IL-1β and IL-1β." (PMID 35308390, 2022). "By using A549 cells devoid of RIG-I/MDA5 and stably expressing TLR3, we did not detect significant IFN expression upon activation of TLR3 by exogenously added poly(I·C) or infection with ZIKV." (PMID 33658344, 2021). "Mice lacking TRIF or TLR3 showed a lower CTL response and impaired viral clearance at the site of infection after HSV-1 flank infection, as compared with WT or MyD88−/- mice." (PMID 34895058, 2021). "This further dissects the IFNα/β responses to separate sensors demonstrating a need, and not a redundancy, for both TLR3 and MDA5 to sense and respond differentially to infection." (PMID 34804036, 2021). "TLR3 and MDA5 mRNA levels were significantly higher in HRV1B infection (p = 0.036 and p = 0.017, respectively), but not in HRV16 infection (p = 0.093 and p = 0.069, respectively)." (PMID 34838080, 2021). "TLR2, TLR3, TLR9, and TLR13 expression patterns showed no significant variations in mRNA expression in koala PBMCs with a range of subtype infection profiles (KoRV-A only vs. KoRV-A with KoRV-B and/or -C)." (PMID 33915914, 2021). "After infection with HPAI virus, Muscovy duck TLR3 was upregulated at 24 HPI in the lung and brain, with sustained expression in the brain (even though this is a non-fatal infection in Muscovy ducks)." (PMID 32477965, 2020). "Continuing studies revealed an almost instant MC degranulation that indirectly depended on TLR3/TRIF signaling, and a delayed MC degranulation triggered by direct infection of MC, not involving TLR3/TRIF signaling." (PMID 32984069, 2020). "On the other hand, the expression of TLR3, IRF-7, OASL1, and OASL2 in tumor cells 8 h post infection showed a significantly negative correlation with the rNDV infection rate." (PMID 29882780, 2018). "Our results showed that the TLR3 mRNA levels from transfected HEK293 cells exhibited no apparent change before and after EV-A71 infection, suggesting that EV-A71-induced TLR3 downregulation was not on the transcriptional level." (PMID 30563052, 2018).
infection (continued). "Unlike the expression level of TLR3 and TLR7, S1PR1 expression in the tested tissues after infection with ZH283 was lower than that in response to infection with SW8." (PMID 28676793, 2017). "Our results demonstrate that poly I:C stimulated sELR1 expression by specifically activating TLR3 and that sELR1 expression was not up-regulated by EIAVFDDV13 infection of eMDM after the knockdown of TLR3 mRNA." (PMID 25106750, 2014). "We confirmed RIG-I up-regulation in skin fibroblasts at 12 h post-infection with a maximum at 36 h post infection, whereas there were no significant changes in RIG, TLR3 and Mda5 expression in the mock-infected cells or the non-treated cells." (PMID 22206025, 2011). "In our study, it was shown that absence of TLR3 reduces the levels of AST and ALT during infection." (PMID 38172683, 2024). "Further, WNV has been demonstrated to evade initial detection by host cells via interaction of WNV NS1 with host pattern recognition receptors, such as RIG-I and TLR3, which may explain the lack of ISG induction we observed upon WNV infection of motor neurons." (PMID 39334427, 2024). "It was, not until recently, found that TLR3 and TLR7, as direct intracellular RNA sensors, were highly activated in SARS-CoV-2-infected CalU-3/MRC-5 multicellular spheroids in the early stage of infection." (PMID 35955436, 2022). "Interestingly, direct infection of isolated alveolar macrophages with PR8 also shows an increase in TLR9, TLR7 and TLR3, with no changes in TLR2, and reduced TLR4." (PMID 30682165, 2019). "The expressions of TLR3 and TLR4 were not modified either by the infection or the supplementations." (PMID 31405262, 2019). "However, in this study, the effect of TLR3 signaling is apparent because the type I IFN response is independent of TLR3 and therefore insufficient to locally control CHIKV replication during the early phase of the infection." (PMID 25452586, 2015). "Since previous studies of the role of TLR3 in WNV infection have revealed both a protective host response as well as enhanced in vivo pathogenesis, we characterized the cell autonomous response to infection in the presence or absence of TLR3." (PMID 25127040, 2014). "Moreover, MEFs isolated from wild-type, TLR-9−/−, TLR-3−/−, MAVS−/− and MyD88−/− and TRIF−/− C57BL/6 mice embryos were all producing similar levels of IFN-β upon MVMp infection, indicating that neither TLRs nor RLRs are involved in the IFN response triggered by replicating MVMp in MEFs." (PMID 37111493, 2023). "Though critical for survival, TLR3 expression does not contribute to protection from CB4-induced T1D, contrary to previous observations in MDA5+/- mice, where a reduction in MDA5 increased survival and protected against the development of T1D after CB4 infection." (PMID 34804036, 2021). "The role of TLR3 in IAV infections has been described elsewhere, as has the importance of TLR3 for the priming which leads to severe secondary infections with S. pneumoniae, but so far the contribution of TLR3 during the secondary infection with pneumococci has not been studied." (PMID 26956584, 2016). "TLR3 sensing of HCV infection is not likely to be restricted to neighboring hepatocytes, as we have demonstrated here, but may also occur in tissue-resident macrophages (Kupffer cells) or monocyte-macrophages recruited to the site of infection." (PMID 23717201, 2013). "Furthermore, even in the absence of poly (I:C) or CVB3 infection, TLR3 still localized to LC3-positive structures, arguing that even under basal conditions, the autophagosome might fuse with TLR3-positive endosomal vesicles." (PMID 24709646, 2013). "However, TLR3 was found significantly upregulated in SJL/J (Bonferroni t-test, p < 0.05, t = 6.358), but its expression in C57BL/6 was not significantly increased by TMEV infection (Bonferroni t-test, p = 0.431, t = 0.802)." (PMID 19094215, 2008).